SIRT1 (sirtuin 1)
Diseases named in the same sentence as SIRT1 in open-access papers (continued):
Sharing a sentence is not in itself a finding about the gene and the disease.
HIV-1 infection (2 papers, 2005 to 2022). The type species of lentivirus and the etiologic agent of acquired immunodeficiency syndrome (AIDS). "These experiments collectively show that the SIRT1 deacetylase activity is required for HIV gene expression and establish SIRT1 as a potential drug target in the treatment of HIV-1 infection." (PMID 15719057, 2005). "Thus, inhibition of SIRT1 due to miR-34a and miR-217 will ease the restriction in terms of deacetylation on Tat, and in turn will enhance HIV-1 infection." (PMID 36685589, 2022). "miR-34a and miR-217 target sirtuin 1 (SIRT1) to enhance HIV-1 infection." (PMID 36685589, 2022). "For future study, it would be of considerable interest to explore the therapeutic potential of miR-34a, as this particular miRNA targets three host proteins (PNUTS, SIRT1, and TASK1) to promote HIV-1 infection." (PMID 36685589, 2022).
intestinal cancer (2 papers, 2019 to 2025). "SIRT1 is often mutated/deleted in intestinal cancers, and restoration of SIRT1 promotes the cytoplasmic retention of β-catenin." (PMID 41304967, 2025). "The ability of SIRT1 to promote cytoplasmic retention of β-catenin has therapeutic implications, as it suggests that SIRT1 activators may be useful in treating intestinal cancers." (PMID 41304967, 2025).
intestinal polyp (2 papers, 2013 to 2020). Discrete abnormal tissue masses that protrude into the lumen of the intestine. "Increased levels of SIRT1 control fibroblast activation and tissue fibrosis, while, SIRT1 inactivation, reduces the growth and number of intestinal polyps in the APC+/min mice model." (PMID 32655835, 2020). "When a SIRT1 transgene was overexpressed in the intestinal epithelium, APC+/min mice developed fewer intestinal polyps, which was attributed to the increased deacetylation and nuclear exclusion of β-catenin and subsequently decreased proliferation rates of the tumor cells." (PMID 23799088, 2013).
iron deficiency (2 papers, 2020 to 2023). "In conclusion, KLF14 inhibits the transcription of IRP2 via recruiting SIRT1, which then causes TfR1 downregulation and ferritin upregulation, resulting in cellular iron deficiency and suppression of HCC cells growth." (PMID 36600258, 2023). "Given the known role of vitamin D and magnesium deficiency in the pathogenesis of many non-communicable disorders, we will test the effects of their co-supplementation in obese women on the readouts of mood and serum levels of BDNF, inflammatory cytokines, and SIRT1." (PMID 32102680, 2020).
iron-overload (2 papers, 2015 to 2018). "We identified the SIRT1/FOXO1 axis as a key pathway involved in iron-overload." (PMID 26638758, 2015). "Iron-overload increased nuclear and acetylated levels of FOXO1 with corresponding inverse changes in SIRT1 levels in the heart corrected by resveratrol therapy." (PMID 26638758, 2015).
Lewis lung carcinoma (2 papers, 2012 to 2024). "In the current study, we isolated vascular endothelial cells from Lewis lung carcinoma (LLC) subcutaneous xenografts in endothelial cell-specific SIRT1 knock-in C57BL/6J mice." (PMID 23028940, 2012).
Lewy bodies dementia (2 papers, 2018 to 2025). "A loss of SIRT1 activity, but not total SIRT activity has been described for cortical tissue samples from patients with PD and other Lewy body diseases." (PMID 40837190, 2025). "Additionally, in a study that looked at the modulation of SIRT1 expression in multiple human neurodegenerative diseases, there was no significant change found in the SIRT1 expression of patient samples of PD and Lewy bodies dementia." (PMID 30532738, 2018).
lumbar disc herniation (2 papers, 2011 to 2022). "Proliferation activity was decreased by SIRT1 treatment in lumbar spinal stenosis and lumbar disc herniation, Pfirrmann grade 3 and grade 4 discs." (PMID 22152608, 2011). "Clinical tissue samples were collected from patients with lumbar disc herniation (LDH), in which the expression of p300, forkhead box O3 (FOXO3), and sirtuin 1 (Sirt1) was determined." (PMID 35907249, 2022).
Marfan syndrome (2 papers, 2020 to 2024). A disorder of the connective tissue. "More recently, we found that H2O2, as well as TGF-β1, a pro-fibrotic cytokine known to be activated in Marfan’s syndrome and to upregulate Nox4 in the vasculature, increases the reversible oxidation of SirT1 in aortic VSM cells (E. Budbazar and F. Seta, unpublished results)." (PMID 32982786, 2020). "Interestingly, this led to the suggestion that, since no targeted therapy has been developed to date for Marfan syndrome, the prevention or reversal of the SirT1 GS-ylated state may represent a new therapeutic strategy to prevent the dissection/rupture of the TAA in these subjects." (PMID 39203889, 2024). "Similarly, resveratrol, but not another putative SirT1 agonist SRT1720, prevented the development of TAA in Fbn1C1041G/+ mice, a model of Marfan’s syndrome, by stimulating an endothelial cell-derived factor, which downregulated miR-29b and upregulated Bcl-2 in VSM cells, inhibiting their apoptosis." (PMID 32982786, 2020).
mesothelioma (2 papers, 2019 to 2021). A usually malignant and aggressive neoplasm of the mesothelium which is often associated with exposure to asbestos. "Here we demonstrate that BAP1 wild-type mesothelioma cells were rendered sensitive to EPZ-6438 upon SIRT1 (Sirtuin 1) silencing/inhibition or when cultured as multicellular spheroids, in which SIRT1 expression was lower compared to cells grown in monolayers." (PMID 34277422, 2021). "In addition, SIRT1 has been shown to play a role in mTOR, AKT, and ER beta signaling in mesothelioma." (PMID 31608237, 2019). "Analysis of sirtuin family members crosstalk revealed that SIRT1 has negative effect on SIRT3 and SIRT5 protein levels in bone cells and this depends on the type of cellular stress, whereas positive effects were recorded in Mero-14 mesothelioma cells." (PMID 31608237, 2019).
Mitral regurgitation (2 papers, 2020 to 2025). An abnormality of the mitral valve characterized by insufficiency or incompetence of the mitral valve resulting in retrograde leaking of blood through the mitral valve upon ventricular contraction. "SIRT1 plays an important role in the process of left atrial fibrosis caused by mitral regurgitation." (PMID 32350389, 2020). "In this study, miniature pigs were used to construct a model of mitral regurgitation to study the regulation of SIRT1 on left atrial fibrosis caused by mitral regurgitation." (PMID 32350389, 2020). "In this study, we found that mitral regurgitation caused fibrotic remodelling, that the content of collagen I was increased significantly and that the content of SIRT1 was significantly reduced." (PMID 32350389, 2020). "Finally, the mechanism and influence of SIRT1 on atrial fibrosis caused by mitral regurgitation needs to be explored and verified." (PMID 32350389, 2020). "Specifically, in a mitral regurgitation model, SIRT1 regulation was observed in the LA, suggesting its potential as a therapeutic target in conditions involving LA fibrosis." (PMID 39636756, 2025). "The regulation of left atrial fibrosis induced by mitral regurgitation by SIRT1 was demonstrated in both animal and cell experiments." (PMID 32350389, 2020). "Thus, we found that SIRT1 expression was significantly decreased during the left atrial fibrosis induced by mitral regurgitation." (PMID 32350389, 2020). "Moreover, no studies on SIRT1 and left atrial fibrosis caused by mitral regurgitation have been conducted previously." (PMID 32350389, 2020).
mucositis (2 papers, 2022 to 2025). Mucositis is inflammation and damage of the mucous membranes lining the mouth and other parts of the gastrointestinal (GI) tract. "Chlorogenic acid alleviates mucositis by activating SIRT1 and reducing inflammation and oxidative stress." (PMID 41425553, 2025). "DOX showed increased osteoclast fusion, differentiation in vitro and in vivo, increased mucositis and changed locomotory behavior and pattern, whereas these phenomena significantly reduced the Sirt1 activator exposure." (PMID 36499492, 2022). "Furthermore, while combining DOX with the Sirt1 activator (RES), the Sirt1 activator significantly rescued the DOX-induced alteration in osteoclast activation, mucositis and locomotory behavior in vitro and in vivo." (PMID 36499492, 2022).
muscle degeneration (2 papers, 2021 to 2025). "However, all these findings taken together are only the beginning of a major study necessary to prove the real efficacy of SIRT1 as a new pharmacological target in the prevention of muscle degeneration in DMD patients, but they can still be considered a good starting point." (PMID 34205021, 2021).
neonatal respiratory distress syndrome (2 papers, 2022 to 2025). "The expression of SIRT1 protein was lower in intestinal tissue of infants with neonatal respiratory distress syndrome during NEC." (PMID 35958178, 2022). "At the time of diagnosis of NEC, the expression of SIRT1 decreased in children with respiratory distress syndrome and CRP level increased." (PMID 35958178, 2022).
nerve inflammation (2 papers, 2022 to 2025). "However, our previous studies have shown that ubiquitous, AAV2-mediated overexpression of SIRT1 also failed to reduce optic nerve inflammation in EAE, although the extent of SIRT1 expression in retinal inflammatory cells is unknown." (PMID 35740955, 2022).
neuronal ceroid lipofuscinosis (2 papers, 2022 to 2023). "In a mouse model of infantile neuronal ceroid lipofuscinosis, treatment with the SIRT1-activator resveratrol was found to increase cellular ATP status and mitochondrial mRNA levels and to increase the lifespan of the mice." (PMID 36142486, 2022). "In studies on neuronal ceroid lipofuscinosis (also called Batten disease), resveratrol was found to increase the NAD+/NADH ratio and levels of ATP, p-AMPK, PGC-1α, and SIRT1, whereas decreased levels of p-S6K1 were observed in cell and mouse models of this disease treated with this compound." (PMID 36344724, 2023).
oligospermia (2 papers, 2024 to 2025). Decreased number of spermatozoa in the semen. "Our results support the hypothesis that various sperm parameters in the state of oligospermia are associated with or caused by reduced levels of SIRT1 and SIRT3 proteins." (PMID 38255792, 2024). "The aim of the present study is to determine the role of SIRT1 and SIRT3 in regulating oxidative stress, telomere shortening, and their association with oligospermia." (PMID 38255792, 2024). "Therefore, we assessed the protein levels of SIRT1 and SIRT3, total antioxidant capacity (TAC), superoxide dismutase (SOD), malondialdehyde (MDA) and catalase activity (CAT) in the seminal plasma of 272 patients with oligospermia and 251 fertile men." (PMID 38255792, 2024).
oral diseases (2 papers, 2021 to 2022). "For example, given most studies focus on roles of SIRT1 in oral diseases, exploring other sirtuins members will extend current knowledge." (PMID 36060706, 2022).
ovarian dysfunction (2 papers, 2020 to 2024). The inability of the ovaries to function. "Here we demonstrated that MG-dependent glycative stress is involved in ovarian dysfunctions associated to PCOS and suggest that this condition contributes to deregulation of SIRT1 functional network, mitochondrial mass and redox milieau and autophagy." (PMID 31947651, 2020). "Overall, present findings demonstrate that MG-dependent glycative stress is involved in ovarian dysfunctions associated to PCOS and support the hypothesis of a SIRT1-dependent adaptive response." (PMID 31947651, 2020).
pheochromocytoma (2 papers, 2022 to 2025).
postpartum depression (2 papers, 2024 to 2025). A type of clinical depression that occurs after childbirth. "The findings suggested that resveratrol enhanced postpartum depression by increasing the activity of SIRT1 and autophagy indicators, reducing the p62 protein expression, and suppressing the activation of AKT and mTOR via inhibition in the hippocampus." (PMID 39494329, 2024). "Resveratrol can potentially reduce postpartum depression in mice by activating SIRT1, enhancing autophagy, and suppressing the mTOR pathway." (PMID 39494329, 2024). "Furthermore, activation of hippocampal SIRT1 has been shown to block the development of postpartum depression-related to increased GR(GRα) expression.Thus, SIRT1 may be a novel target for the treatment of postpartum depression." (PMID 40416964, 2025).
proliferative diabetic retinopathy (2 papers, 2018 to 2023). Advanced retinopathy due to diabetes mellitus characterized by the formation of new vessels in the retina. "A decrease in SIRT-1 levels was also observed in peripheral blood mononuclear cell cultures from patients with proliferative diabetic retinopathy and an increase in interleukin-17, a pro-inflammatory cytokine." (PMID 37371967, 2023). "A recent study of IL17 revealed that SIRT1 plays a protective role in proliferative diabetic retinopathy by suppressing IL17 production." (PMID 30513672, 2018).
protein misfolding diseases (2 papers, 2018). "At the same time, research that elucidates the role of natural polyphenols in activating Sirtuin 1 and affecting pathologies of protein misfolding diseases has increased." (PMID 29976995, 2018). "Such a combination therapy might benefit several age-related metabolic and protein misfolding diseases, where SIRT1 activation holds great promise." (PMID 30463299, 2018).
pulpitis (2 papers, 2022 to 2023). Inflammation of the dental pulp. "Beside the regulatory effect of SIRT1 in defensive response, SIRT1 is also involved in key pathogenic processes in pulpitis such as extracellular matrix (ECM) degradation and angiogenesis." (PMID 36060706, 2022). "In addition, in vitro analysis showed that SIRT1 inhibitors attenuated cell migration and tube-like structures formation in endothelial cells stimulated with LPS and TNF-α, implying a possible pro-angiogenesis role of SIRT1 in pulpitis." (PMID 36060706, 2022).
Renal cyst (2 papers, 2015 to 2024). A fluid filled sac in the kidney. "Consistent with this, we also found increased expression of SIRT1 (1.4×) in human PKD1 renal cysts." (PMID 39000280, 2024).
retinal ischemia (2 papers, 2023 to 2025). A ischemic disease that involves the retina. "This is supported by published data showing that quercetin inhibits oxidative stress induced by retinal ischemia and reperfusion through the SIRT1/FOXO3A pathway." (PMID 40273147, 2025).
retinitis pigmentosa (2 papers, 2019 to 2023). Retinitis pigmentosa (RP) is an inherited retinal dystrophy leading to progressive loss of the photoreceptors and retinal pigment epithelium and resulting in blindness usually after several decades. "This discovery supports SIRT1 as a new driver gene of retinitis pigmentosa and confirms the utility of the RPGeNet model to identify potential IRD candidate genes." (PMID 31712826, 2019). "Upregulation of Sirtuin Type 1 (SIRT1), a nicotinamide adeninedinucleotide (NAD+)-dependent deacetylase, has been proved to protect against ample ocular diseases, while its effect on retinitis pigmentosa (RP) has not been illustrated." (PMID 37388281, 2023).
scleroderma (2 papers, 2021 to 2022). Scleroderma is a rare autoimmune connective tissue disorder characterized by abnormal hardening of the skin and, sometimes, other organs. "Interestingly, activation of SIRT1 with resveratrol was reported to ameliorate both lung and dermal fibrosis in bleomycin-induced scleroderma mice through the inhibition of TGFβ signaling, or by targeting the mTOR pathway, respectively." (PMID 35268452, 2022). "In this context, SIRT1 expression levels were found to be significantly reduced in the skin and dermal fibroblasts of SSc patients, as well as in the lesional skin from mice with bleomycin-induced scleroderma, with SIRT1 activation leading to a mitigation of fibrosis both in vitro and in vivo." (PMID 35268452, 2022).
serous carcinoma (2 papers, 2016 to 2018). "The proportion of SIRT1 expression is significantly higher in serous carcinoma compared with mucinous tumours." (PMID 26800494, 2016). "SIRT1 overexpression is more common in early‐stage serous carcinomas and is correlated with longer OS compared with late‐stage disease." (PMID 26800494, 2016).
sleep disorder (2 papers, 2024 to 2025). A change from the patient's baseline sleeping pattern, in the hours slept and/or an alteration/dysfunction in the stages of sleep. "Finally, the circItm2b/Sirt1/Nox4 signaling axis was validated for its involvement in sleep disorders following TBI." (PMID 39962534, 2025).
ST Elevation Myocardial Infarction (2 papers, 2019 to 2025). A myocardial infarction that produces elevation in the ST segments of the ECG. "The purpose of this study was to investigate the association between SIRT1 single nucleotide polymorphisms (rs7895833 A > G in the promoter region, rs7069102 C > G in intron 4, and rs2273773 C > T in exon 5) and development of premature ST-elevation myocardial infarction ≤45 years." (PMID 31143479, 2019). "SIRT1 protein levels were enhanced and endothelial nitric oxide synthase levels were diminished in ST-elevation myocardial infarction patients regardless of the underlying gene variant." (PMID 31143479, 2019). "SIRT1 levels were markedly elevated in the ST-elevation myocardial infarction group, irrespective of the underlying genotype." (PMID 31143479, 2019). "Interestingly, in line with our preclinical findings, an inverse correlation between baseline levels of SIRT1 and PCSK9 was observed (R = −0.1753, P = 0.0262) which was particularly pronounced in patients with ST-elevation myocardial infarction (r = −0.2306, P = 0.0297)." (PMID 40653676, 2025).
synucleinopathies (2 papers, 2015 to 2018). "Altogether, the accumulated evidence supports a relevant role for SIRT1 in synucleinopathies and definitely, although still controversial, SIRT1 effects on the regulation of autophagy are an important aspect to take into consideration in this complex scenario." (PMID 25946078, 2015). "However, no direct correlations have been drawn on how reduced activity of Sirtuin 1 using pharmacological interventions can possibly improve pathology of synucleinopathies through modulating transcription factors such as CREB." (PMID 29976995, 2018).
T-cell acute lymphoblastic leukemia (2 papers, 2021 to 2024). Acute lymphoblastic leukemia of T-cell origin. "SIRT1 enhances NOTCH1-induced T-cell acute lymphoblastic leukemia (T-ALL) development and mediates resistance to NOTCH1 inhibition in a deacetylase-dependent mechanism." (PMID 39479446, 2024).
testicular cancer (2 papers, 2016 to 2018). A primary or metastatic malignant neoplasm that affects the testis. "In the testis, the role of SIRT1 is reported to be associated with spermatogenesis, fertility, and differentiation, but not testicular cancer." (PMID 30319549, 2018). "Trichostatin A (TSA) could strongly increase miR-449a levels in testicular cancer cell lines and miR-449a down-regulated the histone deacetylase Sirt1." (PMID 26975503, 2016).
testicular degeneration (2 papers, 2019 to 2022). "Several reports have revealed that mTORC1 and SIRT1 are key modulators of aging and age-related male reproductive health disorders, including testicular degeneration and abnormal sperm production." (PMID 31018574, 2019). "In addition, we provide a new therapeutic approach using ACA and B. cereus protease to prevent DOX-induced testicular degeneration by modulating miR-155/SIRT1/FOXO1 network." (PMID 35715546, 2022).